CCL17 (C-C motif chemokine ligand 17)
Diseases named in the same sentence as CCL17 in open-access papers (continued):
Sharing a sentence is not in itself a finding about the gene and the disease.
infection (continued). "Infection with O. dentatum significantly increased expression of IL4, IL13, ARG1, CCL17 and CCL26, with a concurrent trend for down-regulation of the expression of Th1-related genes such as IL8." (PMID 35069576, 2021). "Based on previous results, we resorted to a murine model of CF challenged with A. fumigatus and first evaluated the expression of CCR4 and its ligands CCL17 and CCL22 during infection." (PMID 33669094, 2021). "FACS analysis revealed a significant increase in the proportion of specific DC subsets that expressed CCL17 in the mLN and in the PP after STM infection." (PMID 33945673, 2021). "In this study, we investigated the influence of the pro‐inflammatory chemokine CCL17 on the uptake and dissemination of STM during the early critical phase of infection when bacteria leave the GI tract to initiate systemic infection." (PMID 33945673, 2021). "Of these 7 cytokines/chemokines, only 4 were expressed in wild type at relatively low concentrations, while 3 (CCL20, CCL17, CXCL1) appeared to be uniquely expressed in Nlrx1-/- mice at this early stage of infection." (PMID 32956405, 2020). "Reportedly, chemokines are specialized in the recruitment of various cells, including neutrophils (IL-8), monocytes (CCL2), Th1 cells (CXCL9, CXCL10), Th2 cells (CCL17, CCL21), and Th17 cells (CCL20), to sites of infection." (PMID 32231137, 2020). "It is feasible that the altered macrophage compartment in these knockout animals further promotes a Th2 response by releasing CCL17 and CCL22 chemokines known to recruit Th2 cells to the site of infection." (PMID 31365119, 2019). "Consequently, we propose the following hypothesis in which the infection using Δgra18 strains, which may provide a weaker Th2 chemokine profile (Ccl17, Ccl22, and Ccl24) led to early control and lower chance for long-term persistence in mice than GRA18 wild type parasites." (PMID 30320549, 2018). "(F) CCL17 and CCL22 levels were measured by ELISA from supernatants collected 24 hr after BMDM infection with the indicated strains at an MOI of 1:5." (PMID 30320549, 2018). "Expression of the type 2 chemokine ligands, CCL17 and CCL22 increased as early as 7 days post-infection and remained upregulated up to 21 days of infection, but somewhat surprisingly their receptor, CCR4, was not." (PMID 28103263, 2017). "In RV infected Tbet deficient mice we observed an increase in airway levels of the chemokine CCL17, a ligand for CCR4 which is expressed on Th2 cells, on day 7 post-infection." (PMID 27683080, 2016). "Infection of M2 macrophages with C. pneumoniae resulted in significantly enhanced release of TNF-α, IL-6, IL12p70, IL-12p40, IL-10, CCL17, and CCL24 as compared to uninfected M2 cells." (PMID 26606059, 2015). "FCPLJ treatment downregulated several inflammatory cytokine genes in the liver, including CCL6/MRP-1, CCL8/MCP-2, CCL12/MCP-5, CCL17/TARC, IL1R1, IL1RN/IL1Ra, NAMPT/PBEF1, and PF4/CXCL4, indicating its potential role in mitigating inflammation during infection." (PMID 40007026, 2025). "For the other measured cytokines, IL-1, CXCL10, IL-23, Arginase, CCL17 and IL-12p70 no significant infection- or sex-dependent differences were observed." (PMID 40794782, 2025). "Notably, after 14 and 21 days of infection, the expression levels of CXCL1 and CCL17 significantly increased compared to the H99 infection group." (PMID 39728387, 2024). "However, even given this limitation, clear trends were observed, with increases in the pro-inflammatory cytokines TNFα and IL-1β, the regulatory cytokine IL-1RA and the chemokines CCL2, CCL17 and CCL3 in the sputum post-infection." (PMID 37012228, 2023). "In mLN, there were similar increases in the frequency of CCL17 expression in DC‐A and DC‐B but not in DC‐C and DC‐D, indicating that infection with STM resulted in an increased frequency of CCL17+ cells in some DC subsets." (PMID 33945673, 2021).
infection (continued). "Here, in a flow cytometry analysis of different myeloid cells and with a particular focus on DC subsets, it was demonstrated that CCL17+ DCs not only carried STM and contributed to the transmission of bacteria but also that the expression of CCL17/EGFP was upregulated upon infection." (PMID 33945673, 2021). "However, following infection, obese mice had increased circulating levels of B cell activating factor (BAFF, p = 0.0070), CCL5 (p = 0.0118), CCL17 (p = 0.0118), Chitinase-3-like 1 (p = 0.0118), CXCL5 (p = 0.0118), and IFN-alpha (p = 0.0118)." (PMID 32854687, 2020). "With increased time of infection, the expression of M1 macrophage-related markers, including CD86, CXCL11, and TNF-α decreased, while the expression of M2 macrophage-related markers including CD206, CCL17 and IL-10 gradually increased." (PMID 26091535, 2015). "However, M2-related chemokines CCL2, CCL17, and CCL22 progressively increased during the period of 13 weeks infection." (PMID 24666892, 2014). "The contribution of the surrounding liver tissue, however, was quite significant for other ones, e.g. IL-12, IFN-γ, IL-4 and IL-17A, at the early stage of infection; CXCL9, IL-4, IL-5, CCL17, at the middle stage; and IL-10 and TGF-β at the late stage of infection." (PMID 24637903, 2014). "Given that CCL17 was expressed in RV infected wild type mice on days 1 and 2 post-infection, but did not result in Th2 responses, it would appear however that a lack of Tbet mediated suppression of Th2 differentiation in lymphoid tissue must precede chemokine expression for a Th2 response to occur." (PMID 27683080, 2016). "The analysis showed that CCL17‐expressing DCs are located at the site of STM uptake in the PP and are, at least in part, infected with bacteria, hence the level of CCL17 expression was examined to test whether the production of the chemokine is affected by STM infection." (PMID 33945673, 2021). "Therefore, the results of serum CCL11 and CCL17 concentrations did not support previous findings that these chemokines could also be used as infection markers in individuals with diminished parasite loads." (PMID 30619332, 2018). "Altogether, these results demonstrate a statistically significant, yet modest influence of CCL17 on the spreading of STM from the PP to mLN, but not to systemic organs, in the early phase of infection after oral administration of the bacteria." (PMID 33945673, 2021). "On the other hand, the levels of CCL17, CCL21 and CCL22 were not affected by FusOn-H2 infection, and CCL5 was actually reduced by the virus treatment." (PMID 25460506, 2015). "We detected increased CCL17 levels only in serum of RSV-infected children, which is not surprising since CCL17 is directly induced by infection of respiratory epithelial cells and could be further augmented in the presence of Th2 cytokines." (PMID 25013801, 2014).
cancer (63 papers, 2014 to 2026). A tumor composed of atypical neoplastic, often pleomorphic cells that invade other tissues. "Similarly, high levels of CCL17 and IL-11 are associated with poor outcome in malignant neoplasms due to aggressive biological behavior regarding local invasion and metastasis." (PMID 32793466, 2020). "Although the majority of experimental data on CCL17 in human diseases are focused on cancer, elevated concentrations of this chemokine have also been detected in autoimmune and inflammatory processes." (PMID 38674602, 2024). "High intra-tumoral expression of the C-C motif Chemokine Ligand 17 (CCL17) has been found to promote T cell infiltration of tumors thereby contributing to improved survival in some cancers." (PMID 37435088, 2023). "In contrast, M2→M1 macrophages reprogrammed in the presence of cancer cell spheroids had increased levels of CCL17 (from M2→M1 45 pg/mL to S + M2→M1 113 pg/mL, p = 0.0021) and CCL24 (from 3.3 to 5 ng/mL, p = 0.0356)." (PMID 37445941, 2023). "We also found that TSLP from cancers prepares the metastasis “soil”, such as inducing expression of CCL17 in the lungs to recruit CCR4+ cancer cells and their protector CCR4+FoxP3+ Tregs and Th2-skewed CD4+ T cells." (PMID 36104343, 2022). "It is possible that the location, timing and context of CCL17 expression determines its impact on cancer establishment and progression." (PMID 35226704, 2022). "In contrast, CCL17 has been reported to play a complex and somewhat contradictory role in cancer development and progression." (PMID 35226704, 2022). "This is highly significant for chemokines, as CCL17, which promotes cancer, is dependent on hypoxia." (PMID 33624446, 2021). "When cancer cells treated with CCL17, stemness-related markers were highly expressed, and EMT process was enhanced." (PMID 34745015, 2021). "Seven upregulated genes (≥2.0-fold), Ccl24 (4.8-fold), Ccl17 (3.9-fold), S100a8 (2.9-fold), Tarm1 (2.7-fold), Anxa10 (2.4-fold), Ptgs2 (2.0-fold), and Ccl22 (2.0-fold) were detected as inflammatory and cancer-promoting genes." (PMID 34948416, 2021). "CXCL12, CCL22 and CCL17 have been described as critical factors for T-reg attraction in different cancer types." (PMID 28987144, 2017). "As reported in the literature, CCL17, CCL18 and CCL22, characteristic C-C chemokines released by TAMs, are closely associated with the malignant progression and poor prognosis of a series of cancers." (PMID 39473097, 2025). "Previous research has shown that aberrantly high expression of CCL17 in various cancers, including leukemia, lung cancer, bladder cancer, breast cancer, gastric cancer, and liver cancer, serves as a primary driver for recruiting CCR4-expressing Tregs into the TME." (PMID 38914802, 2024). "CCL17 is known to induce the recruitment of Tregs, specifically in cancer." (PMID 39061147, 2024). "Unlike M2 macrophages, M1→M2 began to secrete certain IL-4-induced chemokines only after co-culture with cancer cell spheroids, for instance, CCL17 (M1→M2: 0.02 ng/mL; S + M1→M2: 0.12 ng/mL, p = 0.0004) and CCL24 (M1→M2: 0.5 ng/mL; S + M1→M2: 2.4 ng/mL, p = 0.0016)." (PMID 37445941, 2023). "Additionally, the mRNA levels of Treg chemokine receptors Ccr4, Ccr8, and Ccr10 as well as their ligands, Ccl1, Ccl17, and Ccl22 are significantly upregulated in the v-rasHa/ΔNp63α carcinomas compared to v-rasHa/Stuffer tumors or normal skin." (PMID 37638000, 2023). "Previous studies also showed that CAFs could produce the chemokine ligand CCL17 to act on CCR4 of cancer cells to improve cancer proliferation and migration." (PMID 35982908, 2022). "CCL22 and CCL17 are produced by cancer cells and are known to induce immune evasion in cancer." (PMID 33163184, 2020). "CCL17 and CCL22 promote stemness of cancer cells with CCR4 expression, drug resistance, stimulate the proliferation of cancer cells, and cause cancer cell migration and EMT, as shown on many types of cancers." (PMID 33182504, 2020).
cancer (continued). "They suggest that the CCL17/CCR4 axis may drive Treg recruitment in a variety of canine cancers." (PMID 33692955, 2021). "In addition, transcription of the chemokines CCL18 and CCL17 was decreased in the cancer group." (PMID 28350008, 2017). "The expression of CCL17 and CCL22 is increased in the lung, liver, and brain of tumor-bearing nude mice with an increased malignancy phenotype of cancer cells." (PMID 39114657, 2024). "For validation, we examined the expression of CCL17, CXCL14, and CXCR3 in cancer and adjacent tissues of six patients with SLC7A11 overexpression by ELISA." (PMID 35517862, 2022). "Some chemokine receptors, such as cCCL27 (8 cancers), CCL28 (7 cancers), CCL16 (5 cancers), CCL17 (5 cancers), and CCL15 (four cancers), were negatively associated with pyroptosis in several cancers." (PMID 35246158, 2022). "Using cytokine profiling, we demonstrated that PFD significantly depleted the secretion of cancer- and invasion-promoting cytokines, particularly IL8, CCL17, and TNF-β." (PMID 34680267, 2021). "TLS in other cancers have been identified and defined by expression of a number of chemokines that are involved in TLS neogenesis: CCL19, CCL21, CXCL12, CXCL13, CCL17, and CCL22." (PMID 34943886, 2021). "Another therapeutic approach is the use of anti-CCR4 antibodies or CCR4 antagonists (receptor for CCL17/TARC and CCL22/MDC) in cancer therapy to reduce the accumulation of Treg and thus enhance the immunotherapy and anticancer response of the immune system." (PMID 32781743, 2020). "CCL17 is a known STAT6 transcriptional target and chemoattractant that recruits various CCR4 + immune cells—such as CD8+ or CD4+ T-cells, and macrophages—in murine and canine cancer models, in addition to human tumors." (PMID 38285120, 2024). "CCR4 and its ligands CCL17 and CCL22 are also involved in cancer cell migration." (PMID 39114657, 2024). "CCL5, XCL1, XCL2, CCL17, CCL22, and CCL19 showed a positive correlation with DEF6 in most cancers, and DEF6 may function in regulating these chemokines in cancer." (PMID 36686789, 2022). "Moreover, it has been shown that the production and secretion of CCL17 within the TME through the CAFs trigger the recruitment of myeloid-derived suppressor cells (MDSCs) to the TME, promoting invasion in various cancers." (PMID 34680267, 2021). "Similar mechanisms were also found in the progression of NSCLC, where highly expressed plasminogen activator inhibitor 1 (PAI-1) enhances the expression of cytokines, including C-C motif chemokine ligand 17 (CCL17), CCL22, IL-6, and TGF-β1, in TAMs to promote cancer progression." (PMID 33114183, 2020). "However, the same chemokines recruit cells that promote the development of cancer, for example CCL17/TARC and CCL22/MDC, CCL20/LARC or CCL19/ELC and CCL21/SLC." (PMID 32781743, 2020). "In addition, using an independent cohort from BC Cancer, where phospho-STAT6 histology data was not available, CCL17 expression was compared in STAT6WT and STAT6D419 mutant patient samples." (PMID 38285120, 2024).
inflammation (7 papers, 2006 to 2022). Aberrant reaction of the microcirculation characterized by movement of fluid and leukocytes from the blood into extravascular tissues. "In the lung, DC and alveolar macrophage depletion protected mice from IL-13-induced airway inflammation, and this protection was associated with reduced CCL17 and CCL22 production." (PMID 29099057, 2017). "Likewise, in intestinal inflammation in mice, CCL17 reduced Treg cell expansion, but promoted IL-12 and IL-23 production by DCs in an autocrine mode and augmented activation of Th1 and Th17 cells." (PMID 29099057, 2017). "We describe here the identification of high affinity neutraligands of CCL17 and CCL22, two chemokines involved in the Th2-type of lung inflammation." (PMID 26442456, 2015). "Furthermore, we identified a positive correlation between serum CCL4 and CCL17 levels, suggesting that serum CCL4 could be a relatively specific marker for type 2 airway inflammation." (PMID 35892679, 2022).
bacterial infection (6 papers, 2015 to 2025). "We showed that CCL17‐expressing cells localize in the vicinity of STM in the SED of PP and that bacterial infection triggered upregulation of CCL17 expression in specific intestinal DC subsets in a tissue‐specific manner." (PMID 33945673, 2021). "The relative MoDC vs. Mo/MP signature encompasses additional genes that participate in “migration of cells” (p = 10−2.3, with S1PR3, CCL17, and SLC2A1), “bacterial infection” (p = 10−3.2, with CD1B, CD209, and FCGR2B), and “synthesis of nitric oxide” (10−2.5, with PLAU, IL1R2, and NOS2)." (PMID 26150816, 2015).
cardiovascular diseases (1 paper, 2025). "Our follow-up study also needs to further confirm whether CCL22 has the same or opposite regulatory mechanism as CCL17 in cardiovascular diseases." (PMID 41266856, 2025).
central nervous system diseases (1 paper, 2022). "CCL17 deficiency has been reported to potentially prolong cardiac graft survival and improve the symptoms of central nervous system diseases." (PMID 35687056, 2022).
neurodegenerative disease (1 paper, 2023). A disorder of the central nervous system characterized by gradual and progressive loss of neural tissue and neurologic function. "However, the levels of CCL17 in normal aging or other neurodegenerative diseases have not been previously investigated." (PMID 37408205, 2023).
CCL17 also shares sentences with these, for which no sentence is quoted: Allergy (17 papers); idiopathic pulmonary fibrosis (8); depression (4); ulcerative colitis (4); autism (3); bladder cancer (3); bullous pemphigoid (3); esophageal squamous cell carcinoma (3); infectious disease (3); systemic sclerosis (3); adenocarcinoma (2); allergic rhinitis (2); chronic rhinosinusitis (2); colorectal cancer (2); conjunctivitis (2); DRESS syndrome (2); endometriosis (2); Erythema (2); fibromyalgia (2); fungal infections (2); inflammatory bowel disease (2); interstitial lung disease (2); lymph node metastases (2); subarachnoid hemorrhage (2); toxic epidermal necrolysis (2); acute myocardial infarction (1); age-related macular degeneration (1); AIDS (1); Airway obstruction (1); amebiasis (1).
A further 67 diseases each share a sentence with CCL17 in 1 paper.